LEP (leptin)
Diseases named in the same sentence as LEP in open-access papers (continued):
Sharing a sentence is not in itself a finding about the gene and the disease.
Obesity (continued). "Given the anorexigenic effects of leptin in the brain, it has become a strong contender in the treatment of obesity." (PMID 35628271, 2022). "Since obesity and diabetes are also associated with an excessive inflammatory response, celastrol acts as a leptin sensitizer in the pharmacological treatment of obesity." (PMID 36263142, 2022). "Based on previous studies focusing on obesity and insulin resistance, we first measured body fat, serum leptin and Fetuin B levels in mice fed a HFD or chow for 12 weeks." (PMID 35896788, 2022). "Although leptin is essential to regulate appetite and increase energy expenditure, its levels are increased in obesity." (PMID 35008925, 2022). "In this study of postmenopausal women, we quantified the mediating effects of leptin and CRP, fasting insulin, and estradiol in explaining the associations between obesity and ER‐positive breast, endometrial, and colorectal cancers." (PMID 35048536, 2022). "LEP rs28954080 (−633C/T) at 5′ UTR is one of the leptin gene SNPs that played significant role in obesity in different populations during literature review." (PMID 36619235, 2022). "In obesity there is a resistance to leptin, despite its high circulating levels, that represents a characteristic of obesity status." (PMID 36278579, 2022). "A product of the obesity gene, leptin takes part in the regulation of body weight by controlling food intake and energy expenditure." (PMID 36422274, 2022). "The leptin-null ob/ob mouse which lacks leptin production is one of the most-used monogenic obese mice in obesity research." (PMID 36613864, 2022). "Analysis of the influence of obesity on serum levels of leptin (correlation indices Pearson's R BMI/abdominal circumference versus leptin)." (PMID 35989732, 2022). "Numerous studies have reported that obesity, insulin resistance, glucocorticoids, estrogens, and chronic inflammation are closely related to the high levels of leptin." (PMID 35198097, 2022). "Primary cilia in the VMH are longer than other neuronal cilia types which are significantly shorter under metabolic conditions such as obesity and leptin resistance." (PMID 36568981, 2022). "Aberrations in leptin expression are one of the most frequent features in the onset and progression of obesity." (PMID 36235638, 2022). "Here, we show a specific proteomic signature of EVs released by MCF-7 breast cancer cells grown in the presence of leptin (Lep-EVs), in attempt to find additional molecular effectors linking obesity to breast cancer biology." (PMID 36361728, 2022). "Chronic low-grade inflammation is a hallmark of both obesity and CRC etiology; leptin itself has already been proven to be an inflammation inducer, along with other inflammatory cytokines." (PMID 35563103, 2022). "We separately collected the obesity and leptin resistance targets from databases like DisGeNET, GeneCards, and NCBI Gene databases." (PMID 35937803, 2022). "Leptin is a product of the obesity gene secreted by fat cells and is thought to play a central role in regulating appetite and energy expenditure." (PMID 35498804, 2022). "Studies in rat Leydig cells have noted that high leptin, similar to that found in obesity, suppresses testosterone secretion." (PMID 36320802, 2022). "Multiple phenotypes of leptin deficiency, including obesity, hyperglycemia, and subfertility, can be reversed by AAV-Leptin administration." (PMID 35563777, 2022). "The results of the study confirm an inhibitor-induced anti-obesity effect that enhanced leptin signalling." (PMID 35563589, 2022). "Nutrient excess, such as the intake of a high-fat diet, reduces hypothalamic responses to exogenously administered leptin and induces dietary obesity; however, orally active components that attenuate neural leptin dysregulation have yet to be identified." (PMID 35597815, 2022). "Leptin, the appetite suppressant hormone, was identified in 1994 as the driving factor for obesity in the ob/ob mice model." (PMID 35164764, 2022).
Obesity (continued). "Animal and human studies have shown that obesity and high-fat diet induce leptin and insulin resistance." (PMID 36615118, 2022). "This is in accordance with a myriad of studies dating back several years that demonstrate that insulin and leptin resistance are important features of obesity, type 2 diabetes, and low-grade inflammation." (PMID 35406000, 2022). "This is partly because obesity increases the levels of adipokines expressed by adipocytes, such as leptin and adiponectin." (PMID 36536397, 2022). "In mothers with overweight or obesity, pre-pregnancy serum leptin levels are already raised, so although they rise less during gestation than in a normal weight pregnancy, they remain higher at term in the mother and fetus." (PMID 36619540, 2022). "Obesity has been known to induce adipokines to release more leptin, which, in turn, is involved in the disease progression of OA." (PMID 35327669, 2022). "Having confirmed the efficacy of our synthetic peptide leptin mimetics in a number of mouse models of obesity and diabetes, we turned our attention to exploring the molecular basis of this activity." (PMID 35527735, 2022). "Two hormones, leptin and resistin, are best known as adipose tissue-specific secretory factors, playing a critical role in obesity and diabetes." (PMID 36612600, 2022). "This leptin-obesity relationship has been reported in a multi-ethnic population as well as in T2DM patients." (PMID 36381191, 2022). "Parallel with obesity, high levels of serum leptin were maintained in mice fed with HFD‐ and PG‐free diets, in both the fasting and feeding stages." (PMID 35154693, 2022). "Adiponectin and leptin levels are inversely related to the progression of obesity, insulin resistance, and atherosclerosis." (PMID 35889740, 2022). "A decrease in the responsiveness of leptin impairs the central regulation of food intake and body weight, ultimately leading to obesity." (PMID 35597815, 2022). "Firstly, the present study confirmed previously reported links between adiposity and hormonal balance, with individuals with obesity having lower levels of ghrelin and higher levels of leptin compared to normal-weight individuals." (PMID 35634372, 2022). "Leptin, a pro-inflammatory adipokine and a key factor of obesity, is suspected to play a major role in these disorders." (PMID 35326405, 2022). "Individuals with obesity tend to have lower levels of circulating ghrelin and higher levels of circulating leptin." (PMID 35454071, 2022). "The ultimate extension of this viewpoint is to regard obesity as a pathological disease because of the failure to appropriately respond to leptin, like the insulin resistance that proceeds β-cell failure in type 2 diabetes, and call it “type 2 obesity”." (PMID 36394061, 2022). "These miRNAs were suspected to target the molecules including STAT3, PI3K, AKT and FOXO1 in leptin signal in obesity, PPARγ and FOXO1 in adipogenesis pathway, and p38MAPK, PPARγ and PPARα in white adipose tissue browning pathway." (PMID 36065413, 2022). "In obesity, excessive secretion of cytokine leptin by adipocytes promotes renal sympathetic nerve activity (RSNA) by stimulating the central nervous system." (PMID 36510119, 2022). "The present study investigated the links between fasting individual olfactory functions and peripheral concentrations of ghrelin and leptin, two hormones highly involved in eating behaviour and previously used as biomarkers for obesity." (PMID 35634372, 2022). "Previous evidence suggested that the suppressor of cytokine signaling 3 (SOCS3) played an essential role in the regulation of energy metabolism homeostasis, which inhibited the activity of insulin and leptin (characteristic feature in human obesity)." (PMID 36145200, 2022). "One of the common pathways which is significantly affected during obesity is leptin signaling pathway." (PMID 35159361, 2022).
Obesity (continued). "Generally, fat deposition promotes leptin secretion; obesity leads to elevated fasting plasma leptin concentrations." (PMID 35659366, 2022). "They showed that leptin concentrations were higher in obese individuals and had a direct correlation with the degree of obesity." (PMID 36556428, 2022). "Obesity, in part through crosstalk with leptin and availability of lipids in the TME, increases the presence of MDSCs and their PD-L1 expression to enhance tumor progression." (PMID 35752704, 2022). "High levels of leptin along with leptin resistance in obesity are not only responsible for establishing a proinflammatory state but also make obese individuals more prone to cardiovascular complications." (PMID 35837388, 2022). "Obesity-induced inflammation is triggered by the secretion of proinflammatory adipokines by adipose tissue, particularly visceral adipose tissue, including leptin, along with a diminution in the synthesis of anti-inflammatory adiponectin." (PMID 36304965, 2022). "MCP1 increases lipolysis and leptin secretion while lowering insulin-stimulated glucose uptake, increasing plasma levels during obesity, contributing to impaired insulin sensitivity." (PMID 35422689, 2022). "It is known that the concentration of leptin increases and the concentration of adiponectin decreases in obesity." (PMID 35164174, 2022). "Several findings revealed the multifaceted direct effects of the obesity hormone leptin in cancer cell metabolism." (PMID 36361728, 2022). "Fasting insulin, HOMA-IR, and leptin levels were significantly elevated in hypothyroid children compared to the control group; more in hypothyroid children with obesity." (PMID 35501770, 2022). "Therefore, understanding leptin and leptin receptor signaling pathways in the pathogenesis of endometriosis will provide new insights for better understanding the association between obesity and endometriosis and also for developing new strategies for treatment." (PMID 36140261, 2022). "Often women with obesity demonstrate metabolic abnormalities such as increased circulating leptin, glucose, insulin, and cholesterol, that play a cumulative and vital role in the development of PE." (PMID 35631228, 2022). "Leptin is an anti-obesity hormone secreted by adipocytes discovered through positional cloning, and it has pleiotropic effects on energy homeostasis as well as endocrine and metabolic physiology and pathology." (PMID 36232527, 2022). "In patients with diet-induced obesity, excess metabolites and lipid consumed in the diet result in high levels of circulating leptin, and the dysregulated leptin signaling maintains adipocyte hypertrophy and obesity." (PMID 34757591, 2022). "Leptin is a master regulator of food intake and body energy balance, and its levels were shown to be increased in obesity, diabetes and cardiovascular diseases." (PMID 36359273, 2022). "Adipose-derived stromal cells isolated from patients with obesity promoted secretion of leptin to regulate ERα+ MCF-7 tumor cell growth and aggressive tumor cell properties." (PMID 35435599, 2022). "They concluded that there are several factors such regulatory systems, including the HPA, gonadal, growth-hormone, leptin axes, the sympathetic nervous system, the central adrenergic, serotoninergic, and dopaminergic systems that are related to obesity." (PMID 35480480, 2022). "Of several variants in LEP, LEPR, and FTO genes identified and tested for obesity association, only a few have been successfully replicated in different world populations." (PMID 36126070, 2022). "Excessive levels of circulating leptin are generally related to an increase in subcutaneous fat and obesity." (PMID 36230104, 2022). "One of the related factors to leptin and obesity is Galectin-3, which belongs to a family of animal lectins that bind beta-galactosides, and is distinguished from others by the inclusion of tandem repeats in its N-terminal region." (PMID 36151575, 2022).
Obesity (continued). "It follows that leptin secretion is increased in obesity, bringing about pro-inflammatory effects, whereas adiponectin synthesis, which is anti-inflammatory, is decreased." (PMID 36575508, 2022). "The process of methylation in gene expression is additionally responsible for leptin secretion involved in regulating satiety and obesity as well as metabolic diseases." (PMID 36220981, 2022). "We used the 25th internal percentile of z-scores of circulating leptin levels as cut-off to identify pre-pubertal children with obesity and with low z-scores of circulating leptin levels." (PMID 35677722, 2022). "In summary, perinatal HFD with maternal obesity induces early postnatal obesity with transiently elevated adipocytokine levels of IL-6 and leptin along with impaired glucose metabolism in the offspring." (PMID 35896539, 2022). "Leptin and ghrelin levels both exhibit diurnal oscillations and are influenced by obesity and food intake." (PMID 36501110, 2022). "Leptin resistance and altered energy balance have been attributed to obesity in TRPV1-null mice fed HFD." (PMID 35455971, 2022). "Adipose tissue produces the hormone leptin and with the expansion of adipose tissue in obesity, the leptin concentration increases." (PMID 35844529, 2022). "Resistance to leptin, impairment of the regulatory outflow of leptin and increased food intake contribute to the impairment of energy homeostasis, which exacerbates the problem of obesity and has serious consequences for the whole body." (PMID 35684517, 2022). "Such efforts should integrate the microbiome–host interplay by means of advanced metagenomics, metatranscriptomics, metaproteomics, and metabolomics, to assess the leptin genetics–gut microbiome–obesity–CRC relationship." (PMID 35563103, 2022). "Currently, the inconsistent and insufficient data related to leptin’s relationship with obesity and CRC indicate the necessity of further related studies." (PMID 35563103, 2022). "Leptin and adiponectin are common adipokines, and obesity increases leptin levels while decreasing adiponectin levels." (PMID 35740306, 2022). "Leptin is increased with both obesity and pregnancy, but in pregnancies with obesity maternal leptin is actually decreased in comparison to lean pregnant women." (PMID 35348641, 2022). "The BPH/5 female offspring present excessive catch up growth after birth, hyperphagia, obesity, cardiomegaly, increased blood pressure, and hyperleptinemia with leptin resistance." (PMID 36065848, 2022). "For example, leptin resistance can be found in many overweight patients and exacerbates their obesity, which leads to metabolic disorders." (PMID 36619557, 2022). "Individuals living with obesity also had higher concentrations of IL-6 and leptin in comparison to normal weight individuals allocated to the corn oil intervention group." (PMID 35958557, 2022). "Short peptides, e.g. setmelanotide, are now in various phases of clinical trials for the treatment of patients with severe obesity due to rare genetic disorders in the leptin-melanocortin pathway." (PMID 35574020, 2022). "The aim of this work was to investigate the relationship between z-scores of circulating leptin levels and the prevalence and the degree of steatosis hepatis in a well-characterized cohort of pre-pubertal children with obesity." (PMID 35677722, 2022). "In humans, leptin is a marker for the development of obesity, and as body fat increases, leptin levels increase." (PMID 36248900, 2022). "While in hypothyroid children with obesity, leptin showed a significant positive correlation with BMI (r = 0.51, P = 0.004) and a significant negative correlation with adiponectin (r = − 0.44, P = 0.015)." (PMID 35501770, 2022). "Saturated fatty acid-palmitate has been suggested to increase ER stress by binding to the Toll-like receptor (TLR-4), and thereby trigger leptin resistance contributing to the development of obesity." (PMID 36512575, 2022).
Obesity (continued). "Leptin has been proposed as a key factor in the regulation of body weight and the development of obesity, since it regulates food intake and energy expenditure through a feedback mechanism between the adipose tissue and the satiety center in the hypothalamus." (PMID 36430774, 2022). "Leptin resistance has been demonstrated in obesity states as a reactive increase due to leptin receptor downregulation." (PMID 35242246, 2022). "The aim of the project is to establish the Polish database of severely obese children and adolescents and to evaluate the prevalence of monogenic forms of obesity in this cohort, with a special focus on leptin–proopiomelanocortin pathway abnormalities." (PMID 36479220, 2022). "Circulating leptin concentrations are closely related to obesity, where higher levels of this hormone are observed in obese individuals." (PMID 35164764, 2022). "Obesity-related hyperleptinemia is an important biomarker for predicting cardiovascular outcomes, suggesting that leptin plays a critical role in obesity-related cardiovascular disease." (PMID 35308138, 2022). "FOXO1 mediated leptin on food intake and the central leptin–melanocortin pathway played a pivotal role in the regulation of obesity by ADCY3." (PMID 36101325, 2022). "We identify mechanisms related to insulin resistance and leptin as mediators of the effects of obesity traits on UF and pre-eclampsia." (PMID 35104295, 2022). "Several maternal obesogenic factors contribute to obesity in offspring, including glucose, FFAs, insulin, leptin, IGF-1 and adiponectin." (PMID 36329895, 2022). "Because of these unique abilities, leptin has been proposed as a potential therapeutic agent in obesity and type 2 diabetes." (PMID 36248900, 2022). "Leptin has been related to antidepressant and anxiolytic effects, but in the presence of obesity, there is a resistance to it, despite being found in the circulation proportionally to the size of the fat mass." (PMID 36138959, 2022). "One of the most influential factors is the adipokine leptin, which is an important molecular mediator of the obesity–breast cancer axis." (PMID 36591465, 2022). "For instance, promoted oxidative stress and suppressed immune system are linked with increases in inflammatory factors and adipokines (TNF, leptin, IL-1β, and IL-6) in obesity." (PMID 35628513, 2022). "ECS action is mediated through CB1 receptors, which are present on human and rodent adipocytes and its knock down leads to leanness, resistance to diet-induced obesity, and enhanced leptin-sensitivity in mice." (PMID 36078578, 2022). "Foetal growth is supported through central leptin resistance mechanisms in healthy women, but placental leptin resistance in women with obesity adversely affects feto-placental growth and development." (PMID 35348641, 2022). "Disruption of central 5-HT signaling via 5-HT2C receptors (5-HT2CRs) induces leptin-independent hyperphagia in mice, leading to late-onset obesity, insulin resistance, and impaired glucose tolerance." (PMID 35163521, 2022). "It is well known that serum leptin, an “anti-obesity” hormone secreted from WAT, increases during WAT increase." (PMID 35742932, 2022). "Treatments aiming to improve leptin sensitivity are considered a promising therapeutical approach against obesity." (PMID 35742928, 2022). "The higher leptin levels in obesity lead to the upregulation of phosphorylated STAT3, which induces PD-1 expression in T cells." (PMID 36466818, 2022). "In obesity, there is a decreased sensitivity to leptin (similar to insulin resistance in type 2 diabetes), resulting in the inability to detect satiety even in large energy reserves and high leptin levels." (PMID 35712481, 2022). "In this study, we investigated leptin and adiponectin as well as IR (HOMA-IR) and their associations with thyroid hormone in both lean and hypothyroid children and adolescents with obesity." (PMID 35501770, 2022).